HDAC1 (histone deacetylase 1)
Diseases named in the same sentence as HDAC1 in open-access papers (continued):
Sharing a sentence is not in itself a finding about the gene and the disease.
ovarian carcinoma (continued). "Our study supports RGS10 genes as targets for demethylating and acetylating therapy and identifies RGS10 de-suppression as a likely contributing mechanism for the clinical efficacy of DNMT1 and HDAC1 inhibitors in the treatment of chemoresistant ovarian cancer." (PMID 24475290, 2014). "Interestingly, EMT-related Snail and Slug transcription factors have been shown to induce a self-renewal program in ovarian cancer by upregulation of Nanog, Oct4, HDAC1&3 and Bmi1." (PMID 22276221, 2012). "Besides, DDB2 participates in sensitizing ovarian cancer cells to cisplatin-mediated apoptosis through the downregulation of the bcl-2 (B-cell lymphoma 2) transcriptional machinery in a HDAC1-dependent (Histone deacetylase 1) manner and the ubiquitylation of the antiapoptotic protein bcl-2." (PMID 31635251, 2019). "RGS10 expression is regulated by DNMT1 and HDAC1, and dysregulation of RGS10 reduces chemoresistance in ovarian cancer cells." (PMID 37649067, 2023). "In a previous study, HDAC1 and HDAC3 were found to bind at the 4-1BBL promoter to downregulate 4-1BBL expression in chemoresistant ovarian cancer cells, resulting in immune escape and suppression." (PMID 35585975, 2022). "We ultimately constructed a histone acetylation modulator-related signature containing 10 histone acetylation modulators, among which HDAC1, HDAC10, and KAT7 can act as independent prognostic factors for ovarian cancer and are related to poor prognosis." (PMID 36172179, 2022). "HDAC1 and HDAC7 are overexpressed in ovarian cancer stem cells (CSC) and have the function of maintaining CSC." (PMID 36505774, 2022). "These aloxyurea derivatives, which contained structural similarity with ricolinostat, depicted selective inhibition of HDAC-1 and HDAC-6 over other HDACs and also displayed satisfactory inhibitory potential against ovarian cancer cells A2780 and A2780CisR." (PMID 36034650, 2022). "Intriguingly, HDAC1 and 7 are over-expressed in cancer stem cells, whereas, HDAC9 and 10 are both essential for homologous recombination in malignant ovarian tumors." (PMID 36034650, 2022). "HDAC1 and HDAC7 are involved in the generation and maintenance of these CSC populations in breast and ovarian cancer cell lines." (PMID 33669182, 2021). "In conclusion, class I HDACs HDAC1 and HDAC2 were highly expressed throughout all ovarian cancer cell lines whereas the other HDAC isoforms are expressed at a much lower level and only in some but not all cell lines." (PMID 31234549, 2019). "In our current study, we demonstrate specific contribution of two important epigenetic regulators, HDAC1 and DNMT1, to the suppression of RGS10 expression in chemoresistant ovarian cancer cells." (PMID 24475290, 2014). "Our results further imply that the increased expression of DNMT1 and HDAC1 results in the generation of repressive complexes which target RGS10 promoters and cooperate in regulating ovarian cancer progression." (PMID 24475290, 2014). "The mRNA expression of DNMT1, DNMT3b, HDAC1 and HDAC2 were particularly prominent in high-grade tumors in ovarian cancers, which indicated that they may be the biomarkers of tumor aggressiveness and proliferation, as their high expression is closely associated with ovarian carcinoma progression." (PMID 23420051, 2013). "A notable aspect of our results is that the level of DNMT3b was correlated with HDAC1 and HDAC2 in ovarian cancer, which demonstrated that the two epigenetic events cooperated in controlling ovarian cancer progression." (PMID 23420051, 2013). "When using HDAC isotype-specific substrates, R306465 showed poor inhibition of deacetylation of an HDAC6-specific synthetic substrate, which was confirmed while analysing HDAC1–3 (H3) and HDAC6 substrates (Tubulin, Hsp90) in A2780 ovarian carcinoma cells." (PMID 18000499, 2007).
ovarian carcinoma (continued). "Another study demonstrated that HDAC1 and HDAC3 can bind at the OX40L promoter to downregulate OX40L expression in chemoresistant ovarian cancer cells, which could potentially induce the immunosuppression of cancer cells to escape from immune responses." (PMID 35585975, 2022). "HDAC1, PEX3, MTMR14, and RB1 had the moderate intensity and high quantity in ovarian cancer." (PMID 33748162, 2021). "Further investigation demonstrated the contribution of HDAC1 and DNMT1 to silencing of RGS10 during acquired chemo-resistance and revealed the importance of HDAC1 and DNMT1 inhibition as an assistant therapeutic approach to overcome ovarian cancer chemo-resistance." (PMID 33680048, 2020). "Our results suggest that HDAC1 and DNMT1 contribute to the suppression of RGS10 during acquired chemoresistance and support growing evidence that inhibition of HDAC1/DNMT1 represent novel therapeutic approaches to overcoming ovarian cancer chemoresistance." (PMID 24475290, 2014). "Our results suggest that HDAC1 and DNMT1 contribute to the suppression of RGS10 during acquired chemoresistance and support inhibition of HDAC1 and DNMT1 as an adjuvant therapeutic approach to overcome ovarian cancer chemoresistance." (PMID 24475290, 2014). "Furthermore, the expression of DNMT1, DNMT3b, HDAC1 and HDAC2 was significantly higher in stage III/IV compared with stage I/II ovarian carcinomas." (PMID 23420051, 2013). "For example, expression of HDAC1 mRNA in human urinary bladder cancer specimens was significantly higher than that in normal controls, and increased mRNA expression of HDCA1 and HDAC2 was detected in ovarian cancer tissues compared with normal tissue samples." (PMID 23110995, 2012). "Furthermore, HDAC1, HDAC2 and DNMT3b cooperated in controlling ovarian cancer progression and the HDACs may upregulate the expression of DNMTs." (PMID 23420051, 2013). "In addition, HDAC1, HDAC2 and DNMT3b cooperated in controlling ovarian cancer progression." (PMID 23420051, 2013). "HDAC1 and HDAC7 maintain cancer stem cells (CSCs), both of which are over-expressed in ovarian cancer CSCs compared to non-stem tumor cells (NSTCs)." (PMID 30064416, 2018).
colon carcinoma (44 papers, 2008 to 2025). "Moreover, the expression of HDAC1 and 2 was associated with poor prognosis in colon cancer patients." (PMID 38258065, 2023). "MAGEB2 binds to histone deacetylase 1 (HDAC1) and activates the transcription factor E2F (E2F) that stimulates the proliferation of colon cancer cells." (PMID 37304127, 2023). "At the same time, the downregulation of pyruvate helps colon cancer cells to avoid cell death due to HDAC1/HDAC3 inhibition." (PMID 36839472, 2023). "It is worth noting that previous ChIP-Seq studies on colon cancer cells found β-catenin-TCF4 on the genomic regions of HDAC1 and DNAJB1." (PMID 36551548, 2022). "Another Western blot analysis on human colon cancer tissues demonstrated that both HDAC1 and CREPT were highly expressed in the tumor tissues in comparison with the paired adjacent tissues." (PMID 36230720, 2022). "The purpose of this study was to assess the capability of quinoa peptides released during the simulated gastrointestinal digestion to affect the viability of human colon cancer Caco-2 cells, and screen peptides with HDAC1 inhibitory activity." (PMID 35053925, 2022). "Immunohistochemistry analyses showed that both CREPT and HDAC1 were strongly stained in colon cancer tissues but weakly stained in the adjacent tissues." (PMID 36230720, 2022). "In a recent study it was reported that 5-aza-CdR and TSA can significantly downregulate DNMT1 and HDAC1 and upregulate p21, p27, and p57 genes expression in colon cancer SW480 cell line separately but their joint application was not investigated." (PMID 33680048, 2020). "To provide experimental evidence for this, we first analyzed endogenous HDAC1–6 levels in the colon cancer cell lines DLD1, HT29, and 293T and showed that all six deacetylases are expressed albeit at different levels." (PMID 30804456, 2019). "Here, we investigated the role of individual HDAC1, 2, and 3 in colon cancer cells DLD-1 and WiDr using different HDACi’s with partially overlapping specificities." (PMID 31083396, 2019). "It has been found that HDAC1, 2, 3, and 8 are overexpressed in colon tumor cells, but the function of individual HDAC in cancer metabolism is still unclear." (PMID 31083396, 2019). "Studies involving the knockdown of HDAC1 have shown that loss of HDAC1 expression blocked mitosis in tumor cells, while HDAC3 silencing reduces the growth of colon cancer cells." (PMID 28397399, 2017). "In this context, the HDACi (S)-2 represented the tool capable of unleashing PP2A activity by inducing HDAC1-mediated downregulation of CIP2A transcription in human colon cancers." (PMID 27029072, 2016). "Treating colon cancer cell lines with HDAC inhibitors or reducing Hdac1 expression suppresses colon cancer cell proliferation, and alters inflammatory signalling." (PMID 25606026, 2014). "As previously stated, oxidative stress promotes HDAC1 upregulation in colon cancer cells." (PMID 38683453, 2024). "Besides, BBR instead of probiotics can significantly increase the level of SB production inhibiting the HDAC1 expression, and the inhibitory effect of SB on the growth of colon cancer cells was stronger than LBH and TSA." (PMID 35572672, 2022). "Furthermore, our results have also found that probiotic was inferior to BBR in increasing butyrate production, suggesting that BBR inhibits the growth of colon cancer cells through the regulation of SB production and HDAC1 expression." (PMID 35572672, 2022). "Generally, these results confirmed that CREPT and HDAC1 are coincidently elevated in colon cancer cells, raising a question that HDAC1 and CREPT might interplay to regulate tumor cell behaviors." (PMID 36230720, 2022). "Furthermore, by Kaplan-meier analysis of TCGA colon adenocarcinoma patients’ gene expression data, we found that high expression of HDAC1 predicts poor prognosis of colon cancer." (PMID 33482915, 2021).
colon carcinoma (continued). "Therefore, we next focus on silencing HDAC1, 2, 3, and 8 individually and investigating the alterations of colon cancer cells (DLD-1 and WiDr) in response to DR4 and DR5-induced apoptosis." (PMID 31083396, 2019). "In the present study, we investigated whether selected plant constituents affect HDAC activity or HDAC1 protein status in the human colon carcinoma cell line HT29." (PMID 23476753, 2013). "Previously, we documented that oxidative stress promoteed RUNX3 mislocalization via HDAC1-induced Src activation and RUNX3 expression inhibition via DNA methylation in colon cancer cells." (PMID 38683453, 2024). "CK decreased histone deacetylase 1 (HDAC1) mRNA and protein expression, modulating histone H3 and H4 acetylation to inhibit growth and induce apoptosis in HT-29 human colon cancer cells." (PMID 37049466, 2023). "Western blot analyses showed that both HDAC1 and CREPT are highly expressed in all colon cancer cells including SW620, SW480, HCT116, and DLD1, but are either not or minimally expressed in the normal colon epithelial cell (NCM460)." (PMID 36230720, 2022). "In conclusion, quinoa peptides may have the potential to protect against cancer development by inhibiting HDAC1 activity and regulating the expression of the cancer-related genes, which indicates that these peptides could be explored as functional foods to alleviate colon cancer." (PMID 35053925, 2022). "To confirm the role of endogenous HDAC1 on CREPT activity, we depleted CREPT and/or knocked down HDAC1 in the colon cancer cell line SW480." (PMID 36230720, 2022). "We recently found that the HDAC1/HDAC2-regulated PP2A subunit PR130 binds and dephosphorylates pS1981-ATM in a PP2A holoenzyme complex in hydroxyurea treated human colon cancer cells." (PMID 34685500, 2021). "Other findings point out that the treatment of colon cancer cells with EGCG significantly increases HATs and reduces HDACs activity, particularly HDAC1." (PMID 32429384, 2020). "They inhibit Class I (HDAC1, 2, 3, and 8) and class II HDACs (HDAC4, 5, 6, 7, 9, and 10) in various cancers including colon cancer, lung cancer, breast cancer, gastric cancer, and pancreatic cancer cells." (PMID 32592383, 2020). "Previously, we reported the effect of DNA demethylating agents and histone deacetylase inhibitors on histone deacetylase 1, DNA methyltransferase 1, and CIP/KIP family in colon cancer." (PMID 32592383, 2020). "Previous studies have shown that knockdown of either HDAC1 or HDAC2 resulted in the sensitization of chronic lymphocytic leukemia cells to Trail-induced apoptosis and a reduction in the proliferation of colon cancer cells." (PMID 30669676, 2019). "Several studies have demonstrated increased expression of the class-I HDACs: HDAC1, HDAC2, and HDAC3, in multiple human cancers, including colon cancer." (PMID 29152115, 2017). "HDAC1 and HDAC3 are overexpressed in colon cancer cells and in primary colon cancer, and siRNA (small interfering RNA) mediated silencing of HDAC1 and HDAC3 in colon cancer cells induced apoptosis." (PMID 22496748, 2012). "In vitro studies with colon cancer cells showed that HIPK2 binds, along with HDAC1, to the HIF-1α gene promoter repressing the HIF-1-mediated transcription of VEGF, in line with data showing that the HIPK2/HDAC1 complex leads to histone deacetylation and control of gene transcription." (PMID 39062921, 2024). "It was reported that HDAC1, HDAC2, and HDAC3 are up-regulated in colon cancer cells." (PMID 38258065, 2023). "Alkyl linkers consisting of 12 carbon atoms resultedin HDAC1/2 and 3 degradation in HCT116 colon cancer cells, while alkyllinkers of 6 carbon atoms, although inhibiting the HDAC1/CoREST complexin vitro, showed no activity in cells." (PMID 35293758, 2022). "Compared with normal colon FHC cells, HDAC6, but not HDAC1, was highly expressed in all of the colon cancer cells examined (HCT-116, DLD1, SW480, HT-29 and SW620)." (PMID 27460191, 2016).
colon carcinoma (continued). "In this study we addressed the question whether the polyphenols chlorogenic acid (CGA), genistein (GEN), and EGCG inhibit HDAC1 expression and/or HDAC activity in intact human colon carcinoma cells." (PMID 23476753, 2013). "However, there was no research about the quinoa derived peptides as HDAC1 inhibitors in colon cancer." (PMID 35053925, 2022). "Nonetheless, our results are consistent with recent observations in HCT116 colon cancer cells, where HDACI treatment or depletion of HDAC2, but not HDAC1, sensitizes towards TNFα-induced apoptosis." (PMID 20398369, 2010).
gastric cancer (43 papers, 2005 to 2025). A primary or metastatic malignant neoplasm involving the stomach. "A high expression level of HDAC1/2 is closely associated with a poor prognosis in gastric cancer." (PMID 38920983, 2024). "The flat panel clone formation assay, Edu assay, and transwell experiment revealed that knocking down the expression of HDAC1 and overexpressing TRIP13 could rescue the inhibition of proliferation, migration, and invasion ability of gastric cancer cells caused by knocking down HDAC1." (PMID 39187490, 2024). "The results indicated that knocking down the expression of HDAC1 significantly repressed the multiplication of gastric cancer cells." (PMID 39187490, 2024). "Transwell assays also revealed that knocking down HDAC1 significantly restrained the migration and invasion ability of gastric cancer cells." (PMID 39187490, 2024). "The effects of knocking down HDAC1 on the proliferation ability of gastric cancer cells were detected through plate clone formation and Edu experiments." (PMID 39187490, 2024). "Studies have confirmed that HDAC1/2 is significantly increased in many human cancers, especially in the invasiveness and carcinogenicity of gastric cancer." (PMID 35686089, 2022). "The expression of HDAC1 is also one of the independent poor prognostic factors for the overall survival and disease-free survival of patients with stomach cancer." (PMID 35686089, 2022). "More specifically, high HDAC-1 expression has been correlated with older patients’ age in gastric carcinoma and with younger patients’ age and male gender in mobile tongue SCC." (PMID 33799478, 2021). "Both DAXX and HDAC-1 were detected in the proteins pulled down by the HA antibody in gastric cancer cells overexpressing DAXX, suggesting that DAXX and HDAC-1 are physically associated within these cells." (PMID 32203224, 2020). "(A) B7-H1 and HDAC1–3 expression in 12 paired gastric cancer (C) and adjacent tissues (A) were determined by western blot." (PMID 30537988, 2018). "We found that HDAC1 expression was negatively correlated with the OS rate of gastric cancer patients (HR = 1.88, 95% CI = 1.14–3.12, P = 0.01)." (PMID 28424407, 2017). "For example, in several studies HDAC1 overexpression was detected in over 54% of gastric cancer tissues in both mRNA and protein levels, but another study found that HDAC1 was downregulated in gastric tumors compared with the level in adjacent non-tumors." (PMID 28424407, 2017). "The proproliferative effect of HDAC4 in gastric cancer cells is consistent with that reported previously for the class I HDACs, HDAC1, -2, and -3." (PMID 24896240, 2014). "Specific anti-HDAC1 and HDAC3 small interfering RNAs (siRNAs) were transfected into GC (gastric cancer) cells, and HDAC1 and HDAC3 expression was significantly decreased." (PMID 25167886, 2014). "In a recent study of gastric cancer, HDAC1 expression was reported to be overexpressed and had prognostic value for gastric cancer." (PMID 22496786, 2012). "Furthermore, analysis of the UALCAN database and the human protein atlas database uncovered that HDAC1 is highly expressed in the transcriptional level and patient tissue samples of gastric cancer." (PMID 39187490, 2024). "Apart from the metabolic role of PAICS, its knockdown was found to induce DNA damage and to impair DNA damage repair by reducing HDAC1/2 deacetylase activity and to enhance the sensitivity to DNA damaging agents like cisplatin in gastric carcinoma in vitro and in vivo." (PMID 37172090, 2023). "For example, HDAC1 expression was increased in colorectal cancer and gastric cancer." (PMID 35053925, 2022).